INS (insulin)
Diseases named in the same sentence as INS in open-access papers (continued):
Sharing a sentence is not in itself a finding about the gene and the disease.
gestational diabetes (continued). "During pregnancy, legumes are beneficial in preventing gestational diabetes and excessive weight gain by maintaining postprandial glucose excursions, blood glucose and insulin levels." (PMID 36107862, 2022). "There are significant clinical implications of these findings for use of long-acting insulin analogues in management of gestational diabetes mellitus." (PMID 36271431, 2022). "The American Diabetes Association (ADA) recognizes metformin as a category B medication that should be used for gestational diabetes mellitus as a second-line medication following insulin." (PMID 36381747, 2022). "Pregnant women with HBV virus infection can lead to islet beta-cell injury, and the decrease of insulin secretion directly induces gestational diabetes mellitus." (PMID 35899024, 2022). "We next examined VDR expression in placentae from pregnancies complicated by gestational diabetes regulated by insulin (A2GDM) and preeclampsia (PE)." (PMID 35712242, 2022). "Additional unanswered issues relate to the glucose threshold for insulin initiation and, if initiated, what the appropriate glucose targets should be (i.e., similar to pre-gestational diabetes or “softer” targets)." (PMID 35627517, 2022). "Currently, dietary control, exercise therapy, and insulin therapy are considered the three main methods for the treatment of gestational diabetes, of which dietary intervention is the most important, effective, and preferred method." (PMID 35036430, 2022). "It is reported that even after adjusting for confounding factors such as BMI and age, the T risk allele in TCF7L2 rs7903146 is associated with early postprandial glucose control failure and insulin treatment needs in women with gestational diabetes." (PMID 36339414, 2022). "For patients with gestational diabetes, glucose control can be performed by intramuscular injection of insulin." (PMID 35910483, 2022). "Myo-inositol, a nutritional supplement that is present in fruits and fibre rich food and available as over-the-counter nutritional supplement, has the potential to prevent gestational diabetes through its insulin sensitising action." (PMID 35277398, 2022). "Third, we did not investigate the clinical information, such as neonatal diseases, the nutritional status, the insulin levels, the body weight gain, the smoking of the mother, and gestational diabetes mellitus." (PMID 35407507, 2022). "At present, insulin is the first choice for the treatment of gestational diabetes mellitus, as an effective drug for blood glucose control." (PMID 35936373, 2022). "In women with gestational diabetes, or overweight or obese adults, low-carbohydrate mixed meals had significantly reduced iAUC in blood glucose and/or insulin." (PMID 35407137, 2022). "Prior to the policy, only 0.3% of all Latina emergency Medicaid recipients with gestational diabetes (2 of 617) received any medication (oral agents or insulin) to manage their blood glucose level." (PMID 35486400, 2022). "There is an increased production of fetal insulin, insulin-like growth factor 1, and leptin, resulting in the stimulation of fetoplacental growth for mothers with gestational diabetes." (PMID 35631166, 2022). "In rodent models of maternal obesity and gestational diabetes, changes in β cell development and organization are found in the offspring that alter insulin production and glucose regulation into adulthood." (PMID 36274855, 2022). "Microbiota populations of Prevotella, Parabacteroides distasonis, and Ruminococcaceae are related to insulin signalling pathway and carbohydrate metabolism, which are also enriched in gestational diabetes mellitus populations." (PMID 36582242, 2022). "Human placental lactogen is one of the most important factors during the development of gestational diabetes, and it is characterized by low insulin sensitivity or insulin resistance (IR) that leads to chronic hyperglycemia during pregnancy." (PMID 36013384, 2022).
gestational diabetes (continued). "The majority of videos (77/115, 67%) contained information about some type of gestational diabetes treatment, including medical nutritional therapy, physical activity, insulin, or oral medications." (PMID 35389355, 2022). "The risk factors for progression to T2DM include maternal age, prepartum and postpartum BMI, family history of T2DM, receipt of insulin for gestational diabetes, and fasting glucose level during pregnancy." (PMID 36360827, 2022). "For instance, differential expression of proteins related to insulin sensitivity is found in EVs in women with gestational diabetes." (PMID 36274855, 2022). "As a result, the maternal islets of Langerhans undergo several changes to increase insulin secretion in order to maintain glucose homeostasis and prevent the development of gestational diabetes." (PMID 35399944, 2022). "The miRNAs enriched in EVs from women with gestational diabetes target insulin and glucose regulatory pathways." (PMID 36274855, 2022). "Of the 836 women on treatment for gestational diabetes, 38 (4.5%) had abnormal blood glucose even after delivery and continued on antidiabetes medication: 14 were on insulin and 24 on orally administered antihyperglycaemic medicines." (PMID 35923278, 2022). "The Metformin in Gestational Diabetes (MiG) trial demonstrated that mothers randomized to metformin, compared with insulin, had reduced maternal weight gain and were less likely to develop gestational hypertension." (PMID 35854327, 2022). "For women with gestational diabetes, the proportion receiving insulin increased from 40% before to 66% after ANC administration." (PMID 33600450, 2021). "A 2016 study found that administration of SCOPA during the second trimester of pregnancy improved insulin sensitivity, fasting plasma glucose levels, and circulating adiponectin levels in patients with gestational diabetes." (PMID 35211087, 2021). "We present a case of a 22-year-old female with the congenital dysplastic right kidney diagnosed with gestational diabetes mellitus after failing a 1-hour oral glucose tolerance test, requiring insulin during pregnancy." (PMID 34804616, 2021). "It has been reported that CA rebalances insulin sensitivity and inflammatory response in gestational diabetes mellitus by suppressing ring finger protein 38 (RNF38) expression." (PMID 34737695, 2021). "A study among Chinese women showed that the risk allele-A of rs3733359 of VDBP gene was associated with a modest increase of risk for gestational diabetes mellitus (GDM) in the obese subgroup, where other SNPs demonstrated correlations with insulin and glucose homeostasis." (PMID 35010965, 2021). "The proband is a 20‐year‐old male, who was born at 38 weeks of gestation to a mother with insulin‐controlled gestational diabetes." (PMID 33156547, 2021). "But if your body can’t make enough insulin or stops using insulin as it should, your blood sugar levels rise, and you get gestational diabetes." (PMID 33995276, 2021). "Outcomes included lipids, inflammation markers, insulin resistance, mode of delivery, infant size, pre-eclampsia, and gestational diabetes." (PMID 34444958, 2021). "Accumulated studies have suggested that microRNAs (miRNAs) participate in the pathogenesis of gestational diabetes mellitus by regulating β cell development, insulin sensitivity, and resistance." (PMID 34007244, 2021). "Some mothers are unable to compensate adequately for this hormone-induced insulin insensitivity, and gestational diabetes ensues." (PMID 35128441, 2021). "Gestational diabetes is managed with conventional medications like insulin and oral antidiabetics such as metformin, in addition to diet and exercise." (PMID 34395632, 2021). "Regarding pathology in pregnancy, gestational diabetes (GD) and GD with insulin were similarly distributed in both groups." (PMID 34682679, 2021).
gestational diabetes (continued). "Insulin-treated gestational diabetes mellitus in a previous pregnancy, maternal Sjögren’s syndrome and antenatal depression have all been associated with negative gestational age acceleration." (PMID 33926538, 2021). "The dominant medications used in the management of gestational diabetes according to the papers reviewed were insulin and metformin." (PMID 34395632, 2021). "Apart from gestational diabetes mellitus necessitating insulin therapy, the pregnancy was uneventful." (PMID 33557282, 2021). "Taken together, our study demonstrates a beneficial effect of inulin in the control of gestational diabetes, and this effect is related to the activation of insulin signaling pathway." (PMID 34952629, 2021). "The proband’s younger sister (II-2, aged 40) had insulin-treated gestational diabetes when aged 31 and was diagnosed to have T2D at the age of 38 during screening (FPG 170 mg/dL, A1C 7.7%)." (PMID 34630320, 2021). "Of all women with gestational diabetes, 52 (53%) were treated with insulin and 47 (47%) with dietary advices only." (PMID 34945134, 2021). "Our results highlight an increased expression of LRP1 and LPL in placentas of insulin-treated gestational diabetes and, in turn, an increase in the intracellular ROH apparatus by the non-STRA6 pathway." (PMID 34945773, 2021). "Gestational diabetes mellitus is a pathophysiological state in which there is insufficient insulin available to maintain glucose concentrations in normal range, and hyperglycaemia occurs." (PMID 34658643, 2021). "Insulin sensitivity in peripheral tissues is only slightly decreased during gestational diabetes mellitus compared with healthy pregnant mothers." (PMID 33627830, 2021). "Gestational diabetes mellitus occurs when increased insulin resistance and hyperglycaemia is observed in the middle of the pregnancy." (PMID 33627830, 2021). "Asian-born women did not present an elevated risk of birthing a large for gestational age infant, in either the diet controlled, or insulin requiring gestational diabetes mellitus groups." (PMID 34556066, 2021). "Pregnant women develop gestational diabetes mellitus (GDM) when they cannot overcome elevated insulin resistance by increasing insulin secretion." (PMID 34834527, 2021). "This is a retrospective study conducted from January to April 2020 on patients of gestational diabetes mellitus undergoing either metformin, insulin, or both therapies admitted to the gynecology ward, Rehman Medical Institute (RMI)." (PMID 34589334, 2021). "Metformin showed better effects on feto-maternal outcomes in patients with gestational diabetes in comparison to insulin." (PMID 34589334, 2021). "We aimed to assess the comparative efficiency and safety of the use of glyburide, metformin, and insulin in gestational diabetes mellitus (GDM)." (PMID 34641848, 2021). "This study aimed to evaluate the effects of probiotic supplements on blood glucose, insulin resistance/sensitivity, and prevention of gestational diabetes mellitus (GDM) among pregnant women." (PMID 34603479, 2021). "A RCT of supplementation of 200 μg/day of selenium for 6 weeks in 70 women with gestational diabetes found significant improvements in fasting glucose, serum insulin, C-reactive protein, and oxidative stress." (PMID 34071548, 2021). "On the one hand, pancreas islet cells become hypertrophy and hyperplasia, on the other hand, glucose stimulates insulin secretion to adapt these changes, resulting in elevated blood glucose, even developing gestational diabetes." (PMID 33930086, 2021). "Insulin is the gold standard for the treatment of gestational diabetes, but there are some disadvantages, such as poor patient compliance." (PMID 33429755, 2021). "Associations of maternal early-pregnancy glucose and insulin concentrations with DNA methylation may be more apparent when using fasting glucose and insulin concentrations or among higher risk populations, as observed in studies in women with gestational diabetes." (PMID 32894192, 2020).
gestational diabetes (continued). "In women with Gestational diabetes mellitus (GDM) insulin sensitivity is reduced even further and GDM is defined as decreased glucose tolerance developed during pregnancy." (PMID 32069857, 2020). "In particular, 1.72% (17/988) of all the women were taking hypoglycemic drugs or insulin at the time of follow-up; excluding cases affected by pre-gestational diabetes, the 0.77% (7/977) of women had begun taking these drugs only years after delivery." (PMID 32198414, 2020). "Our study population is relatively healthy with on average lean women, with limited variability in maternal early-pregnancy glucose and insulin concentrations and with a low percentage of women who developed gestational diabetes." (PMID 32894192, 2020). "The previous reports elaborated that primary main factors of gestational diabetes are an insufficient insulin secretion during pregnancy periods." (PMID 32880218, 2020). "Gestational diabetes mellitus (GDM) can appear during pregnancy when insulin insensitivity is increasing." (PMID 33126498, 2020). "There was no information about the degree of glucose control during pregnancy; however, the number of GDM-2 cases (gestational diabetes mellitus treated with insulin) was small (4.2%)." (PMID 32213887, 2020). "Here, we investigated the effects of insulin treatment on the frequencies of immune cell subpopulations as well as T cell-derived cytokines in type 2 diabetic (T2D) pregnancy compared to gestational diabetes mellitus (GDM)." (PMID 32626786, 2020). "One of the most common medical disorders in pregnancy is gestational diabetes mellitus (GDM) which is characterized by insufficient secretion of insulin in response to increased insulin resistance resulting in hyperglycaemia." (PMID 33194786, 2020). "The “metabolic” category consists of studies (n=5) evaluating the consumption of probiotic yogurt on gestational diabetes mellitus, insulin, heavy metal toxicity, calcium, and serum lipid profiles." (PMID 32864237, 2020). "Gestational diabetes mellitus (GDM) is a pathological state in which pancreatic β cells cannot release adequate insulin to meet the increased insulin demand." (PMID 33292292, 2020). "The proband’s mother had gestational diabetes mellitus during both pregnancies, requiring insulin treatment during the first pregnancy." (PMID 31989990, 2020). "Gestational diabetes occurs for the period of pregnancy due to insufficient insulin response, which is usually gone after the baby birth." (PMID 32880218, 2020). "Great attention is paid to the group of pregnant women who have either pre-existing diabetes or gestational diabetes, and especially those under insulin therapy." (PMID 32079162, 2020). "Fifty-two of all women with gestational diabetes were treated with insulin and 47 with dietary advices only." (PMID 32923415, 2020). "On the other hand, fetal overgrowth is observed in gestational diabetes mellitus (GDM) in which increased circulating AA levels interact with insulin sensitivity, and increased maternal glucose stimulates nutrient transport over the placenta." (PMID 32825593, 2020). "The Mysore Pathenon Cohort and the MAASTHI cohorts in India have contributed to our understanding of gestational diabetes and insulin sensitivity and their intergenerational effects such as adiposity in offspring." (PMID 32645067, 2020). "In pregnant women with gestational diabetes, glyburide can be an alternative to insulin despite concerns about its transplacental transfer." (PMID 32379777, 2020). "Leanness with impaired insulin secretion is deeply involved in Japanese gestational diabetes mellitus." (PMID 31275653, 2019). "A 50-60% decrease in insulin sensitivity is seen with advancing gestation both in women with normal glucose tolerance and in women with gestational diabetes." (PMID 31828161, 2019). "Naringenin improves insulin sensitivity in gestational diabetes mellitus mice in an AMPK-dependent manner." (PMID 31591391, 2019).
gestational diabetes (continued). "In contrast, in pregnancies of women without prior ADD use, the most commonly used products were glyburide and insulin, and most of these users were diagnosed with gestational diabetes." (PMID 31775682, 2019). "The rate for Gestational diabetes was 18.3% (n = 183) in the overall sample and 40.9% (n = 75) of them were treated with insulin therapy." (PMID 31107890, 2019). "When this insulin resistance cannot be overcome, despite the hyperplasia of B cells, gestational diabetes occurs." (PMID 31770385, 2019). "Several randomized controlled trials and observational studies, which compared glyburide to insulin for gestational diabetes, showed the two therapies to be comparable in achieving glycemic control." (PMID 31775682, 2019). "None of the mothers in the study had chronic diabetes but 34 of the 882 neonates were born to mothers with gestational diabetes, five of which received insulin treatment." (PMID 31031804, 2019). "Metformin treatment for gestational diabetes alters the postnatal growth trajectory compared to insulin treatment." (PMID 31386659, 2019). "There is currently no COS for studies assessing the follow-up of women diagnosed with gestational diabetes treated with insulin/oral hypoglycaemic agents." (PMID 30611300, 2019). "This study used robust methods to develop the first COS relevant to the follow-up of women with previous gestational diabetes treated with insulin and/or glucose-lowering agents." (PMID 31273408, 2019). "In conclusion, our findings favor insulin treatment in terms of placental vascular circulation, and support recently published guidelines indicating insulin as the preferred medication in gestational diabetes treatment." (PMID 30873116, 2019). "Primary outcomes were serum insulin at late gestation, incidence of gestational diabetes mellitus (GDM) for mothers, and cord blood C-peptide level of neonates." (PMID 30998227, 2019). "We performed a systematic review of 28 studies that included 3,976 mothers who were randomised to metformin or insulin for treatment of gestational diabetes." (PMID 31386659, 2019). "TNF-α has also been found to correlate inversely with insulin sensitivity in pregnant women with normal glucose tolerance and in women with gestational diabetes." (PMID 31828161, 2019). "Metformin is increasingly offered as an acceptable and economic alternative to insulin for treatment of gestational diabetes mellitus (GDM) in many countries." (PMID 31386659, 2019). "Our study suggested therapeutic potential of insulin to treat developmental defects in newborns suffering from gestational diabetes." (PMID 30973884, 2019). "Health outcomes measured in the interventions included gestational weight gain, fasting insulin, fasting glucose, gestational diabetes, gestational age (weeks), and infant birth weight (kg)." (PMID 31675954, 2019). "The aim of this article is to present a protocol for a study to develop a COS for trials and other studies in the follow-up at 1 year and beyond of women with gestational diabetes treated with insulin and/or oral hypoglycaemic agents." (PMID 30611300, 2019). "Zhang reported that the insulin signaling pathway was down-regulated in the placenta of women with gestational diabetes mellitus." (PMID 31406573, 2019). "There are several effective treatment strategies available for gestational diabetes, including using metformin or insulin to control high blood sugars in the mother." (PMID 31386659, 2019). "Low GI diets were found to limit the incidence of excessive birth weight (macrosomia, unrelated to fat mass), and importantly to reduce the use of insulin in those with gestational diabetes mellitus." (PMID 31242690, 2019). "Although insulin was traditionally recommended for gestational diabetes requiring drug treatment, oral antidiabetic agents have recently been considered as potential alternatives, because of their better acceptance, lower cost, and easier administration." (PMID 31232936, 2019).